EGFR (epidermal growth factor receptor)
Diseases named in the same sentence as EGFR in open-access papers (continued):
Sharing a sentence is not in itself a finding about the gene and the disease.
metastatic colorectal cancer (continued). "Given its pivotal role in tumor biology, targeting the EGFR signaling axis at various molecular levels has become a key therapeutic strategy, especially in the treatment of metastatic colorectal cancer." (PMID 40832614, 2025). "We verified the significance of GWMS as a predictive factor for the efficacy of anti-EGFR antibodies in the second-line treatment of metastatic colorectal cancer." (PMID 38862615, 2024). "Increasing evidence indicates that mutations in the BRAF oncogene are not only tied to a poorer prognosis but also correlate with reduced efficacy of anti-epidermal growth factor receptor antibodies in treating metastatic colorectal cancer (mCRC)." (PMID 39119381, 2024). "Anti-EGFR therapy is recommended based on the mutational status of several critical genes such as BRAF (V600E), PIK3CA, and KRAS (exon 2) in metastatic colorectal cancer." (PMID 38339232, 2024). "In our study, the PFS for metastatic colorectal cancer patients after 12 months of anti-EGFR monoclonal antibody treatment was 13.8%, and after 24 months, it was 4.1%." (PMID 39202071, 2024). "GWMS was a predictive factor for the efficacy of anti-EGFR antibodies in the second-line treatment of metastatic colorectal cancer." (PMID 38862615, 2024). "Mutations in RAS and BRAF genes are widely recognized as the primary drivers of resistance to anti-EGFR agents in metastatic colorectal cancer (mCRC)." (PMID 39064004, 2024). "The emergence of anti-EGFR therapies has significantly improved survival outcomes in metastatic colorectal cancer patients, with high response rates in RAS wild-type cases." (PMID 39727997, 2024). "A link between KRAS gene mutations and the therapeutic response was initially observed in individuals with metastatic colorectal cancer who were treated with anti-epidermal growth factor receptor (EGFR) agents." (PMID 39673361, 2024). "Circulating tumor (ct) DNA analysis can be used for diagnosing and monitoring tumor evolution in patients with metastatic colorectal cancer who are treated with EGFR inhibitors." (PMID 39064004, 2024). "Panitumumab is a human immunoglobulin monoclonal antibody designed to target the epidermal growth factor receptor (EGFR) which is used in the treatment of metastatic colorectal cancer alone or in combination with chemotherapy." (PMID 38605419, 2024). "In this article, we reported three clinical cases to illustrate the relevance of RAS mutations identified in ctDNA samples of patients with wild-type metastatic colorectal cancer who received an EGFR inhibitor plus chemotherapy as first-line treatment." (PMID 39064004, 2024). "Primary resistance to anti-EGFR therapies affects 40% of metastatic colorectal cancer patients harbouring wild-type RAS/RAF." (PMID 38467828, 2024). "The clinical significance of FOLFOXIRI (5-FU, leucovorin, oxaliplatin, and irinotecan) plus anti-EGFR monoclonal antibody using cetuximab for metastatic colorectal cancer (mCRC) remains controversial." (PMID 39587053, 2024). "In a recent PROSPECT-C trial on metastatic colorectal cancer (CRC) patients, the aberrations in the RAS pathway and their association with resistance to anti-EGFR treatment in metastatic CRC were investigated." (PMID 38339232, 2024). "The purpose of this study was to assess the ability of metabolic parameters, radiomic features, PET-CT, and clinicopathological data to detect EGFR, BRAF, and KRAS mutation status in metastatic colorectal cancer patients (mCRC)." (PMID 39722096, 2024). "This nonrandomized controlled trial evaluates anti–epidermal growth factor receptor (EGFR) rechallenge therapy in patients in Italy with circulating tumor DNA (ctDNA) RAS/BRAF wild-type (wt) metastatic colorectal cancer." (PMID 38592721, 2024). "The genome-wide DNA methylation status (GWMS) predicts of therapeutic response to anti-epidermal growth factor receptor (EGFR) antibodies in treating metastatic colorectal cancer." (PMID 38862615, 2024).
metastatic colorectal cancer (continued). "The study is testing its combination with cetuximab, an EGFR inhibitor, in KRAS-mutated metastatic colorectal cancer patients." (PMID 38790167, 2024). "GWMS measured using the modified MethyLight assay is a predictive factor of the clinical outcomes of anti-EGFR antibody therapy in the second-line treatment of metastatic colorectal cancer." (PMID 38862615, 2024). "Panitumumab is an immunoglobulin (Ig) G2 mAb that blocks EGFR; IgG2 mAb is FDA-approved for the treatment of patients with EGFR-expressing, metastatic colorectal cancer." (PMID 39239273, 2024). "Cetuximab, a chimeric IgG1 monoclonal antibody targeting the epidermal growth factor receptor (EGFR), has revolutionized personalized treatment of metastatic colorectal cancer (mCRC) patients." (PMID 38254903, 2024). "Emergence of acquired resistance limits the efficacy of the anti-EGFR therapies cetuximab and panitumumab in metastatic colorectal cancer." (PMID 38711991, 2024). "Epidermal growth factor receptor (EGFR) inhibition with monoclonal antibodies represents a cornerstone of treatment for RAS wild-type metastatic colorectal cancer." (PMID 39727997, 2024). "Anti-EGFR therapy plus doublet chemotherapy is standard of care for patients with RAS wild-type metastatic colorectal cancer (mCRC) but the role of triplet chemotherapy is unclear." (PMID 39587053, 2024). "In metastatic colorectal cancer patients harboring KRAS mutations (KRAS G12C), treatment with EGFR inhibitors or monoclonal antibodies yields minimal benefit." (PMID 39770538, 2024). "The results of this meta-analysis confirm the feasible and effective strategy with intensification triplet chemotherapy plus anti-EGFR antibody in patients with initially unresectable metastatic colorectal cancer." (PMID 37978547, 2023). "Although anti-EGFR mAb cetuximab and panitumumab have improved the clinical response and overall survival of metastatic colorectal cancer patients, several unmet needs remain." (PMID 37509078, 2023). "The intensification triplet chemotherapy plus anti-EGFR antibody scheme was feasible and effective in patients with initially unresectable metastatic colorectal cancer." (PMID 37978547, 2023). "A meta-analysis of the use of EGFr-targeted therapy also suggested that saving EGFr-targeted monotherapy until the third line is an effective option in wild-type metastatic colorectal cancer." (PMID 37296984, 2023). "The development of anti-epidermal growth factor receptor (anti-EGFR) monoclonal antibody, cetuximab or panitumumab, is a milestone in metastatic colorectal cancer treatments." (PMID 37310146, 2023). "The survival of metastatic colorectal cancer patients has improved significantly in the last 20 years with the introduction of target-oriented drugs, anti–epidermal growth factor receptor (EGFR), and anti–human epidermal growth factor receptor-2 (HER2)." (PMID 37228916, 2023). "Rechallenge with epidermal growth factor (EGFR) inhibitors represents a promising therapeutic strategy in patients with refractory RAS/BRAF wild-type metastatic colorectal cancer (mCRC)." (PMID 37046778, 2023). "The meta-analysis aimed to assess the clinical efficacy of chemotherapeutic triplet‐drug regimen combined with anti‐EGFR antibody in patients with initially unresectable metastatic colorectal cancer (mCRC)." (PMID 37978547, 2023). "KRAS mutation in tumor tissue is a well-known predictor of resistance to the treatment of anti-EGFR antibodies in metastatic colorectal cancers (mCRC)." (PMID 37511664, 2023). "Bevacizumab and cetuximab are prominent FDA-approved agents that hinder VEGF and EGFR signaling, significantly enhancing outcomes in metastatic colorectal cancer patients." (PMID 37686423, 2023). "Monoclonal antibodies against EGFR are commonly used in the treatment of metastatic colorectal cancer, and some of these agents synergistically inhibit both EGFR phosphorylation and ABCG2 drug efflux activity." (PMID 37445716, 2023).
metastatic colorectal cancer (continued). "The interaction of the MEF2 family with EGFR inhibits cell proliferation in drug-resistant metastatic colorectal cancer." (PMID 37394466, 2023). "AXL is a predictor of poor survival and of resistance to anti‐EGFR therapy in RAS wild‐type metastatic colorectal cancer." (PMID 36409270, 2023). "Capecitabine is one of the drugs used as a first-line treatment in metastatic colorectal cancer, in combination with irinotecan, oxaliplatin, or the targeted agents bevacizumab and EGFR inhibitors." (PMID 37830744, 2023). "This article reports the results of a study that evaluated the combination of the MEK1/2 inhibitor binimetinib and the EGFR inhibitor panitumumab in patients with RAS -mutant or BRAF wild type/RAS wild-type metastatic colorectal cancer." (PMID 37597246, 2023). "The detection of KRAS mutations in tumor tissue is a well-known predictor of resistance to the treatment of anti-epidermal growth factor receptor (EGFR) antibodies in metastatic colorectal cancer (mCRC)." (PMID 37511664, 2023). "This review assesses current evidence on the prognostic or predictive effect of HER2 amplification/overexpression on anti-EGFR treatment outcomes in patients with RAS wild-type metastatic colorectal cancer." (PMID 37463037, 2023). "This study aimed to validate BRAFV600E/RNF43 co-mutations as predictive biomarkers of benefit to anti-EGFR/BRAF therapy, using clinical data from the Flatiron Health-Foundation Medicine real-world clinico-genomic metastatic colorectal cancer database." (PMID 36779536, 2023). "Rechallenge with anti-EGFR drugs represents a promising strategy in refractory RAS/BRAF wild-type (WT) metastatic colorectal cancer (mCRC)." (PMID 37046778, 2023). "By targeting the vascular endothelial growth factor (VEGF) and EGFR pathways, anti-angiogenic agents and EGFR inhibitors have revolutionized the treatment landscape for metastatic colorectal cancer." (PMID 37686423, 2023). "The BEACON CRC study was conducted to evaluate the efficacy and safety of the combination of the BRAF inhibitor (encorafenib), MEK inhibitor (binimetinib), and EGFR inhibitor (cetuximab) in BRAFV600E–mutant metastatic colorectal cancer patients." (PMID 37686423, 2023). "Targeted monoclonal antibody therapy against Epidermal Growth Factor Receptor (EGFR) is a leading treatment modality against metastatic colorectal cancer (mCRC)." (PMID 36979659, 2023). "Monoclonal antibodies targeting EGFR such as cetuximab or panitumumab represent a major step forward in the treatment of RAS wild type (WT) metastatic colorectal cancer (mCRC)." (PMID 36860319, 2023). "Therapeutic options for metastatic colorectal cancer (mCRC) are very limited, and the prognosis using combination therapy with a chemotherapeutic drug and a targeted agent, e.g., epidermal growth factor receptor or tyrosine kinase, remains poor." (PMID 37511431, 2023). "Cetuximab proved to be effective as a first-line treatment for EGFR-positive metastatic colorectal cancers, in combination with FOLFIRI, in a CRYSTAL trial." (PMID 37686423, 2023). "Cetuximab is a monoclonal antibody blocking the epidermal growth factor receptor (EGFR) in metastatic colorectal cancer (mCRC)." (PMID 36668877, 2023). "Only the use of an anti-EGFR agent as a first-line treatment for metastatic colorectal cancer significantly influenced survival results." (PMID 36980549, 2023). "Next, the number of EpCAM + EGFR + cells in blood samples of patients with metastatic colorectal cancer was determined." (PMID 35035479, 2022). "It is used to recognise metastatic colorectal cancer patients who can benefit from anti-EGFR (epidermal growth factor receptor) therapy." (PMID 36092905, 2022). "Primary tumour sidedness is not only an important prognostic factor in metastatic colorectal cancer, but it is also predictive as it affects the response to anti-EGFR-directed therapies." (PMID 35637412, 2022).
metastatic colorectal cancer (continued). "Background and Aims: In patients with Rat sarcoma proto-oncogene (RAS) wild-type metastatic colorectal cancer (mCRC), anti-epidermal growth factor receptor (EGFR) antibodies have been established in first- and further therapy lines." (PMID 35406413, 2022). "The OPUS study is an open-label, randomized, multicenter phase II study, which included 337 newly treated mCRC patients with EGFR-expressing metastatic colorectal cancer who were randomized to receive FOLFIRI alone or combined with cetuximab." (PMID 35433839, 2022). "When the effect of anti-EGFR mAbs was analyzed in patients with metastatic colorectal cancer with wild-type KRAS only, clinically relevant response rates increased to approximately 60%." (PMID 35035479, 2022). "The FIRE-6 trial combined chemotherapy with PD-L1 inhibition and EGFR inhibition in patients with metastatic colorectal cancer." (PMID 35936668, 2022). "Cetuximab is an anti-epidermal growth factor receptor (EGFR) monoclonal antibody used as a single agent in patients with KRAS metastatic colorectal cancer, for which many patients acquire resistance." (PMID 35203305, 2022). "In patients with RAS wild-type metastatic colorectal cancer (mCRC), an anti-epidermal growth factor receptor (EGFR) monoclonal antibody plus chemotherapy is a standard option for treatment in the first-line setting." (PMID 36818675, 2022). "Cetuximab, a monoclonal antibody directed against the EGFR, has been widely used to treat metastatic colorectal cancer; nevertheless, many patients who initially respond to cetuximab develop resistance." (PMID 35897925, 2022). "In patients with metastatic colorectal cancer harboring wild-type RAS, skeletal muscle loss during anti-EGFR therapy combined with chemotherapy predicted poor prognosis." (PMID 36471329, 2022). "For instance, patients with metastatic colorectal cancer expressing EGFR can be treated with anti-EGFR monoclonal antibodies (mAb)." (PMID 35035479, 2022). "Sidedness of primary tumor is a well-established prognostic marker and is predictive for anti-EGFR efficacy in RAS/BRAF wild-type metastatic colorectal cancer (mCRC) patients." (PMID 35158793, 2022). "The present study explored the role of liquid biopsy-driven rechallenge strategy with EGFR blockade in molecularly and clinically selected metastatic colorectal cancer patients." (PMID 35530345, 2022). "The prognosis of locally advanced or metastatic colorectal cancer (mCRC) with wild-type (WT) RAS has improved due to the introduction of new targeted therapies such as epidermal growth factor receptor (EGFR) inhibitors." (PMID 35607541, 2022). "In recent years, corroborating evidence has established epidermal growth factor receptor (EGFR) inhibitors to provide a distinct clinical benefit for patients with Rat sarcoma proto-oncogene (RAS) wild-type metastatic colorectal cancer (mCRC)." (PMID 35406413, 2022). "Current guidelines recommend anti-epidermal growth factor receptor monoclonal antibodies (anti-EGFR Ab) as first-line treatment only in patients with left-sided RAS wild type (RASwt) metastatic colorectal cancer (mCRC)." (PMID 35242708, 2022). "Epidermal growth factor receptor (EGFR) is an effective target for those patients with metastatic colorectal cancers that retain the wild-type RAS gene." (PMID 36575233, 2022). "Study has showed that RAS amplification should as a predictor of anti-EGFR therapy in metastatic colorectal cancer." (PMID 35223996, 2022). "Cetuximab is approved by the FDA for patients with KRAS wild-type metastatic colorectal cancer expressing EGFR and head and neck squamous cell carcinoma." (PMID 36575233, 2022). "With the introduction of molecular-targeted drugs such as anti-EGFR monoclonal antibody therapies and angiogenesis inhibitors, treatment options for patients with metastatic colorectal cancer have changed considerably." (PMID 35444939, 2022).
metastatic colorectal cancer (continued). "For example, EGFR ligand expression is a promising predictive marker for treatment with EGFR inhibitors in metastatic colorectal cancer." (PMID 36077668, 2022). "The epidermal growth factor receptor (EGFR) overexpression is found in metastatic colorectal cancer (mCRC)." (PMID 35578244, 2022). "Panitumumab is a fully recombinant IgG2 human monoclonal antibody targeting EGFR with restricted approval to metastatic colorectal cancer treatment alone." (PMID 36434607, 2022). "Primary tumor sidedness (left vs. right) has prognostic and predictive impact on anti-EGFR agent efficacy and thus management of metastatic colorectal cancer (mCRC)." (PMID 35158793, 2022). "The COIN study assessed the effect of the addition of an anti-EGFR monoclonal antibody (Cetuximab) to continuous chemotherapy on the survival in patients with metastatic colorectal cancer." (PMID 34521767, 2021). "Doublet chemotherapy (e.g., FOLFOX or FOLFIRI) in combination with a biologic agent (anti-EGFR or anti-VEGF) are established first-line treatments against metastatic colorectal cancer (mCRC)." (PMID 34407800, 2021). "Cetuximab is an epidermal growth factor receptor (EGFR) inhibitor used in the treatment of metastatic colorectal cancer, metastatic non-small cell lung cancer, and head and neck cancer." (PMID 34831449, 2021). "The evidence for BRAF mt as a poor prognostic indicator is strongest in metastatic colorectal cancer (mCRC), with worse OS and resistance to EGFR inhibitors." (PMID 34940086, 2021). "Since the introduction of targeted agents, anti-VEGF and anti-EGFR therapy have become part of the standard treatment arsenal for patients with metastatic colorectal cancer (mCRC)." (PMID 34253874, 2021). "Few data regarding post-induction management following first-line anti-epidermal growth factor receptor (EGFR)-based doublet regimens in patients with left-sided RAS/BRAF wild-type metastatic colorectal cancer (mCRC) are available." (PMID 34778029, 2021). "Herein, we report a case of wild-type RAS/BRAF metastatic colorectal cancer (CRC) with resistance to anti-EGFR monoclonal antibody and chemotherapy." (PMID 34888240, 2021). "Anti-EGFR monoclonal antibodies have been approved for the treatment of metastatic colorectal cancer and head and neck cancer." (PMID 34360915, 2021). "The care of metastatic colorectal cancers is based on combination chemotherapies including 5-fluorouracil, oxaliplatin, irinotecan, and monoclonal antibodies targeting the epidermal growth factor receptor or vascular endothelial growth factor." (PMID 34771635, 2021). "Treatment strategies inhibiting BRAF in combination with EGFR have been developed in patients with BRAFV600E mutant metastatic colorectal cancer, but intrinsic and secondary resistance remains a challenge." (PMID 33204026, 2021). "The scFv targeting epidermal growth factor receptor (EGFR) was derived from cetuximab, a monoclonal antibody approved for treatment of metastatic colorectal cancer." (PMID 33863363, 2021). "Analyses of trials assessing anti-angiogenic agents and EGFR inhibitors in first-line metastatic colorectal cancer showed modest correlations between PFS and OS (R2 range, 0.45–0.69)." (PMID 34381708, 2021). "The development of secondary resistance (SR) in metastatic colorectal cancer (mCRC) treated with anti-epidermal growth factor receptor (anti-EGFR) antibodies is not fully understood at the molecular level." (PMID 34271981, 2021). "Anti-Epidermal Growth Factor Receptor (EGFR) antibodies are widely used in patients for RAS wild type metastatic colorectal cancer (mCRC) from first-line therapy to salvage lines." (PMID 34593037, 2021). "This study enrolled 609 patients with metastatic colorectal cancer who were treated with anti-EGFR therapy." (PMID 34188197, 2021).